GAS5 (growth arrest specific 5)
Diseases named in the same sentence as GAS5 in open-access papers (continued):
Sharing a sentence is not in itself a finding about the gene and the disease.
head and neck squamous cell carcinoma (5 papers, 2013 to 2024). A squamous cell carcinoma that arises from any of the following anatomic sites: lip and oral cavity, nasal cavity, paranasal sinuses, pharynx, larynx, and salivary glands. "The findings of the current study correspond to the results of a real-world database in which the expression of GAS5 is correlated with the GAS5 SNP rs145204276 variants and severe tumor grading of head and neck squamous cell carcinoma." (PMID 33925911, 2021). "Furthermore, the data from the TCGA were applied to evaluate the correlation between GAS5 level and head and neck squamous cell carcinoma." (PMID 33925911, 2021).
heart failure (5 papers, 2021 to 2025). Inability of the heart to pump blood at an adequate rate to meet tissue metabolic requirements. "In this study, we explored the functional role of lncRNA GAS5, a widely reported tumor suppressive gene, in hypoxia‐injured H9c2 cells, aiming to evaluate the importance of lncRNA GAS5 in heart failure caused by MI." (PMID 37506155, 2023). "Additionally, unfolding studies on lncRNA GAS5 have shed light on its role in regulating apoptosis, autophagy, and inflammation in the context of heart failure." (PMID 38250803, 2023). "However, the specific role of GAS5 in heart failure is yet to be determined." (PMID 38250803, 2023). "Finally, unmeasured confounders such as comorbidities (e.g. heart failure) and medication effects were not accounted for, which may influence GAS5 expression patterns." (PMID 40685500, 2025).
Hyperglycemia (5 papers, 2019 to 2024). An increased concentration of glucose in the blood. "Hyperglycemia-associated upregulation of lncRNA GAS5 may be a key, modifiable factor contributing to impaired wound healing." (PMID 35464754, 2021). "Of note, their findings suggest that hyperglycemia induces overexpression of GAS5 which subsequently results in a greater production of the pro-inflammatory macrophage phenotype." (PMID 35464754, 2021). "Combined these results suggest a mechanism of hyperglycemia-mediated chronic inflammation that involves the dysregulation of GAS5 expression, leading to elevated production of pro-inflammatory (M1-like) macrophages and abnormal fibroblasts." (PMID 35464754, 2021). "Since GAS5 down-regulation robustly impaired β-cell function, the authors hypothesized that GAS5 induction might be part of a β-cell compensatory mechanism to hyperglycaemia." (PMID 33628198, 2020). "Also, serum lncRNA GAS5 resulted as an independent protective factor of fasting blood glucose, indicating that down-regulation of lncRNA GAS5 may induce hyperglycemia." (PMID 37821982, 2023).
lymphoma (5 papers, 2014 to 2026). A malignant (clonal) proliferation of B- lymphocytes or T- lymphocytes which involves the lymph nodes, bone marrow and/or extranodal sites. "To explore whether GAS5 plays a role in regulating protein translation in lymphoma cells, we first detected the association of GAS5 with the translation initiation factor eIF4E since the initiation of translation is a key step in translation regulation." (PMID 25197831, 2014). "GAS5 lncRNA has recently been reported to co-precipitate with the eukaryotic translation initiation complex in lymphoma cells, suggestive of a possible role in gene translation." (PMID 26198250, 2015). "Like YBX1, the translation of another regulator of cell proliferation, c-Myc (which itself up-regulates cyclins and down-regulates p21), is negatively controlled by GAS5 lncRNA in lymphoma cells, as discussed later (see Section 7.3)." (PMID 26198250, 2015). "GAS5 lncRNA has recently been identified as a novel target for miR-21, which functions as an oncogene in various types of solid tumour and lymphoma." (PMID 26198250, 2015). "RNA-IP results showed that GAS5 was enriched with eIF4E as compared with IgG control in all the lymphoma cell lines, Jeko, Mino, Granta and JVM2, as well as in HEK-293T cells." (PMID 25197831, 2014). "GAS5 was enriched with eukaryotic translation initiation factor-4E (eIF4E) in an RNA-immunoprecipitation assay using lymphoma cell lines." (PMID 25197831, 2014). "GAS5 suppresses miR-21, an oncogene in numerous solid tumors and lymphoma, and FGF1, a regulator of proliferation and apoptosis, so it can be considered as a mediator of the GAS5/miR-21 axis." (PMID 34771549, 2021).
malignant pleural mesothelioma (5 papers, 2014 to 2021). A malignant neoplasm that arises from mesothelial cells in the pleura and shows a diffuse growth pattern. "In malignant pleural mesothelioma patients, the plasmatic circulating levels of GAS5 resulted decreased after chemotherapy." (PMID 34356875, 2021). "In malignant pleural mesothelioma (MPM), GAS5 (growth arrest specific transcript 5) underexpression was observed compared to normal mesothelial tissue." (PMID 26448935, 2015).
papillary thyroid carcinoma (5 papers, 2018 to 2025). "LncRNA Gas5 acts as a sponge for miR-222-3p to activate the progression of papillary thyroid carcinoma by modulating PTEN." (PMID 32432654, 2020). "And then we examined the expression level of Gas5 in papillary thyroid carcinoma cells and identified the function of Gas5 by applying forced expression approaches." (PMID 29423063, 2018). "LncRNA Gas5 serves as a ceRNA to activate PTEN/AKT pathway via sponging miR-222-3p in papillary thyroid carcinoma." (PMID 30406146, 2018). "Taken together, our study provides experimental evidence that Gas5 functions as a competing endogenous RNA to regulate PTEN expression by sponging miR-222-3p in papillary thyroid carcinoma." (PMID 29423063, 2018).
renal carcinoma (5 papers, 2018 to 2026). A carcinoma arising from the epithelium of the renal parenchyma or the renal pelvis. "Preliminary functional exploration revealed that the proliferation, invasion and migration abilities of renal carcinoma cells were repressed by an upregulated Gas5 expression." (PMID 29308053, 2018).
Stroke (5 papers, 2019 to 2024). Sudden impairment of blood flow to a part of the brain due to occlusion or rupture of an artery to the brain. "Compared to the cited study, our cohort of samples is larger, and moreover, we explored the influence of GAS5 haplotypes, environmental factors, and stroke subtypes on IS susceptibility." (PMID 33937403, 2021). "Moreover, to examine whether the impacts of GAS5 variants were restricted to a particular subset, we stratified the IS patients into stroke subsets according to the TOAST categorization." (PMID 33937403, 2021). "Clinical cohort studies have indicated that levels of GAS5 are elevated in the bloodstream of stroke patients, linking this elevation to an increased stroke risk." (PMID 40789569, 2024). "Silencing of the transcription factor Forkhead box O1 (FoxO1) via the lncRNA GAS5/miR-378a-5p/Hspa5 axis in mice significantly improved neurological function recovery in intracerebral hemorrhage, which is the most devastating stroke subtype." (PMID 37987360, 2023). "Previous investigations have identified key stroke-sensitive lncRNAs involved in epigenetic regulation, such as FosDT, HOTAIR, H19, GAS5, MEG3, XIST, and TUG1." (PMID 40789569, 2024). "While most studies in the field have focused on the functional roles of long noncoding RNAs (lncRNAs) NEAT1, GAS5, and HOTAIR in CVS, less attention has been paid to their clinical relevance to stroke incidence and prognosis." (PMID 36439973, 2023).
ulcerative colitis (5 papers, 2017 to 2025). An inflammatory bowel disease involving the mucosal surface of the large intestine and rectum. "In addition, our data showed that there was clear declining tendency of GAS5 expression in the serum from normal controls to ulcerative colitis patients to CRC patients, suggesting that GAS5 could be related to inflammation." (PMID 28099146, 2017). "Interestingly, data obtained from our cohort highlight a negative correlation between GAS5 levels and the clinical scores PUCAI (Pediatric Crohn’s Disease Activity Index) and PCDAI (Pediatric Ulcerative Colitis Activity Index)." (PMID 31652976, 2019).
allergic rhinitis (4 papers, 2021 to 2023). Inflammation of the nasal mucous membranes caused by an IgE-mediated response to external allergens. "Long non‐coding RNA growth arrest‐specific 5 (lnc‐GAS5) and its targets (microRNA [miR]‐21 and miR‐140) are involved in the development and progression of allergic rhinitis (AR)." (PMID 34473845, 2021). "GAS5 suppresses Th1 differentiation and promotes Th2 differentiation via EZH2 inhibition, thus eliciting the development of allergic rhinitis." (PMID 34781960, 2021).
diabetic retinopathy (4 papers, 2020 to 2024). "Consequently, the study indicates that lncRNA GAS5 plays a crucial role in diabetic retinopathy pathogenesis and further studies are needed to clarify its therapeutic potential." (PMID 33374507, 2020).
ischemia (4 papers, 2021 to 2025). A hypoperfusion of the BLOOD through an organ or tissue caused by a PATHOLOGIC CONSTRICTION or obstruction of its BLOOD VESSELS, or an absence of BLOOD CIRCULATION. "Examination of the brain cells of ischemia people showed the GAS5 and PTEN RNA overexpression but the miR-21 underexpression." (PMID 37620425, 2023). "However, other lncRNAs, such as Meg3, Malat1, GAS5, NEAT1, and LOC105374325 mediated the renal cell apoptosis caused by ischemia." (PMID 36552750, 2022). "Moreover, GAS5 was also found to be highly expressed in neurons subjected to oxygen–glucose deprivation/reoxygenation, and knockdown of GAS5 protects against ischemia/reperfusion-induced brain damage and improves overall neurological functions in vivo." (PMID 34054430, 2021).
nasopharyngeal carcinoma (4 papers, 2017 to 2021). A carcinoma arising from the nasopharyngeal epithelium. "GAS5 polymorphisms rs2067079 and rs6790 serve as predictive biomarkers for platinum-based, concurrent, chemoradiotherapy-induced severe myelosuppression and neutropenia among patients with nasopharyngeal carcinoma." (PMID 32354045, 2020). "Moreover, two GAS5 SNPs, which included rs2067079 and rs6790, were associated with a higher possibility of toxic reaction after platinum-based concurrent chemoradiotherapy in patients with nasopharyngeal carcinoma." (PMID 33925911, 2021). "Previous studies prompted that certain functional SNPs within the promoter region of GAS5 could regulation its expression, and were related to risk of cancers, among which rs6790 were suggested as a biomarker for chemoradiotherapy induced toxic reactions in nasopharyngeal cancer patients." (PMID 31905737, 2019). "In current study, we aim to evaluate the effects of SNPs in lncRNA GAS5 on clinical early toxic reactions and treatment efficacy in patients with nasopharyngeal carcinoma receiving chemoradiotherapy in a Chinese population." (PMID 28977945, 2017). "However, the role of GAS5 in nasopharyngeal carcinoma (NPC) remains elusive." (PMID 28977945, 2017).
neutropenia (4 papers, 2017 to 2022). A decrease in the number of neutrophils found in the blood. "Previous study indicated that NPC patients carrying lncRNA GAS5 rs2067079 CT genotypes were more likely to experience chemoradiotherapy induced severe myelosuppression and severe neutropenia." (PMID 35990252, 2022). "In conclusion, in this two stage discovery-validation study, we highlighted two potential functional locus, GAS5 rs2067079 and rs6790 for chemoradiotherapy induced severe myelosuppression and severe neutropenia among NPC patients for the first time." (PMID 28977945, 2017).
oral squamous cell carcinoma (4 papers, 2019 to 2021). "A previous study that surveyed a similar ethnicity showed a lower level of GAS5 in the oral squamous cell carcinoma." (PMID 33925911, 2021). "For example, FoxO1 facilitated transcription of GAS5 to promote propofol‐induced oral squamous cell carcinoma apoptosis." (PMID 34346162, 2021). "The miR-663a targets ZBTB7A that transcriptionally suppresses lncRNA GAS5 under ER stress, and lncRNA GAS5 suppresses tumor cell proliferation and EMT in oral squamous cell carcinoma via regulating the miR-21/Pten axis." (PMID 31608229, 2019). "On the other hand, the presence of GAS5 could suppress tumor invasion and proliferation via the miR-21/PTEN axis in the oral squamous cell carcinoma." (PMID 33925911, 2021).
acute kidney injury (3 papers, 2019 to 2024). Sudden and sustained deterioration of the kidney function characterized by decreased glomerular filtration rate, increased serum creatinine or oliguria. "This genetic association links fluctuations of GAS5 expression owing to gene variations to the exacerbation of renal failure in diabetic individuals." (PMID 39239549, 2024). "However, the involvement of lncRNA growth arrest specific 5 (GAS5) in acute kidney injury (AKI) remained largely unexplored." (PMID 32257391, 2020).
bladder tumor (3 papers, 2018 to 2020). "The analysis of our screening cohort highlighted the significant reduced expression of GAS5 in bladder tumours compared to their matched adjacent normal urothelium, as well as the ability of GAS5 to discriminate bladder tumours from their normal counterparts." (PMID 30374124, 2018). "The expression analysis revealed that GAS5 levels are significantly downregulated (p = 0.001) in bladder tumours compared to the matched adjacent normal specimens in 67.4% of the screened patients." (PMID 30374124, 2018). "ROC curve analysis highlighted the ability of GAS5 reduced levels to discriminate bladder tumours from the matched normal urothelium (AUC: 0.623; 95% CI: 0.562–0.684; p < 0.001), which was also confirmed by logistic regression analysis (OR: 0.339; 95% CI: 0.188–0.614; p < 0.001)." (PMID 30374124, 2018). "Here, we confirmed that there was a negative correlation between GAS5 level and bladder tumor clinical stage." (PMID 29445179, 2018).
cerebral infarction (3 papers, 2019 to 2023). An ischemic condition of the brain, producing a persistent focal neurological deficit in the area of distribution of the cerebral arteries. "GAS5 levels are shown to be increased in rodents following cerebral infarction and GAS5 binds to miRNAs such as miR-365a-3p, miR-137 in vitro." (PMID 36609440, 2023). "It was reported that intracerebroventricular injection of GAS5 shRNA significantly decreased brain GAS5 expression, inhibiting miR-23a, reducing brain infarct size, and improving recovery of neurological function." (PMID 30967760, 2019).
cholangiocarcinoma (3 papers, 2022 to 2025). A carcinoma that arises from the intrahepatic biliary tree (intrahepatic cholangiocarcinoma) or from the junction, or adjacent to the junction, of the right and left hepatic ducts (hilar cholangiocarcinoma). "GAS5 also enhanced cholangiocarcinoma progression by regulating hsa-miR-1297 through direct binding." (PMID 35059460, 2022).
demyelinating disease (3 papers, 2017 to 2021). A broad group of disorders that affect the myelin sheaths that cover the neurons. "Our work suggested that GAS5 was a promising target for the treatment of demyelinating diseases such as MS." (PMID 28808113, 2017). "In summary, the data presented here demonstrated a novel role for GAS5 in microglial polarization and the pathogenesis of demyelinating diseases." (PMID 28808113, 2017). "Gene GAS5 (with FDR = 3.11×10−19) was shown to have a novel role in microglial polarization and the pathogenesis of demyelinating diseases which suggested the potential therapeutic benefit of targeting GAS5 for the treatment of neurological disorders including AD." (PMID 33798195, 2021). "In a recent study, the researchers identified the lncRNA GAS5 as an epigenetic regulator of microglial polarization and suggested that GAS5 may be a promising target for the treatment of demyelinating diseases." (PMID 29392896, 2018). "Thus, GAS5 may be a promising target for the treatment of demyelinating diseases." (PMID 28808113, 2017).
epilepsy (3 papers, 2022 to 2023). A brain disorder characterized by episodes of abnormally increased neuronal discharge resulting in transient episodes of sensory or motor neurological dysfunction, or psychic dysfunction. "In summary, GAS5 exerted an influence on the inflammatory response and cell apoptosis in epilepsy." (PMID 37653173, 2023). "Besides, the regulation effect of LncRNA GAS5 in epilepsy was also involved in the regulation of Calmodulin-dependent protein kinase II (CaMKII)γ/N-methyl-D-aspartate receptor (NMDAR) pathway." (PMID 36278003, 2022). "The other lncRNA is growth arrest-specific 5 (GAS5) which was deregulated in neuronal diseases like epilepsy and its silencing prohibited the KCNQ3 expression via miR-135a-5p sponging to block the epilepsy progression." (PMID 37620425, 2023). "Dysregulated lncRNA GAS5, miR-219, and the CaMKIIγ/NMDAR pathway were studied in epilepsy." (PMID 37653173, 2023).
experimental autoimmune encephalomyelitis (3 papers, 2017 to 2022). An autoimmune demyelinating disease of the central nervous system that is produced experimentally in animals by the injection of homogenized brain or spinal cord in Freund's adjuvant. "Interference with GAS5 in transplanted microglia attenuates the progression of experimental autoimmune encephalomyelitis (EAE) and promotes remyelination in a lysolecithin‐induced demyelination model." (PMID 28808113, 2017). "A previous study has reported that GAS5 promoted microglial M1 polarization and suppressed M2 polarization via the inhibition of TRF4 transcription in a mice model of experimental autoimmune encephalomyelitis." (PMID 35743389, 2022).
glaucoma (3 papers, 2019 to 2023). Increased pressure in the eyeball due to obstruction of the outflow of aqueous humor. "In a translimbal laser photocoagulation-induced chronic glaucoma rat model, shRNA targeted for GAS5 could help to relieve glaucoma symptoms, which are manifested by reduced RGC apoptosis." (PMID 37391006, 2023). "In addition, lncRNA GAS5 has been demonstrated to be a key regulator in glaucoma, because of its ability to regulate the TGF-β/Smads pathway." (PMID 31391457, 2019).
intervertebral disc degeneration (3 papers, 2020 to 2024). "A recent study indicates that GAS5 upregulation is related to intervertebral disc degeneration due to its proapoptotic effects." (PMID 32967315, 2020). "Besides, Wang and colleagues have observed that GAS5 overexpression in nucleus pulpus cells repressed Bcl-2 and upregulated caspase-3, suggesting lncRNA GAS5 is a potential therapeutic target for intervertebral disc degeneration." (PMID 32967315, 2020). "The role of lncRNA growth arrest specific 5 (GAS5) in degenerative nucleus pulposus cell (NPC) apoptosis has been reported, but the mechanism of GAS5 in extracellular matrix (ECM) synthesis in intervertebral disc degeneration (IDD) remains unknown." (PMID 34413821, 2021).
Klinefelter syndrome (3 papers, 2019 to 2022). A sex chromosome disorder caused by the presence of an extra X chromosome in the male karyotype. "The lncRNA GAS5, previously associated with cancer, Klinefelter syndrome, and autoimmune diseases, has been linked to DS." (PMID 35682796, 2022). "In another study on a small cohort of patients with Klinefelter syndrome, the authors showed a 5-fold increase in GAS5, suggesting that an alteration in its levels can be involved in different disorders." (PMID 35682796, 2022).
liver cirrhosis (3 papers, 2020 to 2024). "A previous report revealed that GAS5 is downregulated in liver cirrhosis and forms a reciprocal repressive regulatory loop with miR-222." (PMID 32413995, 2020). "In addition, downregulated liver GAS5 in patients with liver cirrhosis was also confirmed in Yu’s study." (PMID 36979495, 2023). "Interestingly, liver cirrhosis displayed a distinct lncRNA profile: UCA1 upregulation and downregulation of LINC00152 and GAS5 (p = 0.02, 0.001, and 0.001, respectively)." (PMID 39609501, 2024).